BRAF (B-Raf proto-oncogene, serine/threonine kinase)
Diseases named in the same sentence as BRAF in open-access papers (continued):
Sharing a sentence is not in itself a finding about the gene and the disease.
melanoma (continued). "The most frequent genetic alteration described in melanoma is BRAF mutation, present in roughly 50% of the patients, according to the COSMIC database (Catalogue Of Somatic Mutations In Cancer)." (PMID 35805902, 2022). "Nonetheless, patients with melanoma often fail to respond to BRAFi/MEKi despite harboring V600 BRAF mutations, and in some cases, responses have been noted to BRAFi monotherapy despite progression on a prior course of treatment with a different BRAFi." (PMID 35486732, 2022). "Melanomas with BRAF class 1 mutations harbored fewer amplifications of GAB2 (FDR = 0.099), CCND1, and PAK1 (both FDR = 0.18)." (PMID 35706047, 2022). "In other studies, KRAS mutation has been found in melanoma patients who progressed following combined BRAF and MEK inhibition therapy." (PMID 35814395, 2022). "Advances in the understanding of the genetic mutations operating in melanoma pathogenesis have led to revolutionary progress in targeted therapies that interfere with mutation drivers like BRAF." (PMID 35693795, 2022). "Two studies with a similar set-up, published 2017, led to registration of targeted therapy for BRAF-mutated melanoma with dabrafenib and trametinib as well as of the immunotherapy with nivolumab irrespective of BRAF-mutation status." (PMID 35059911, 2022). "On 30 July 2020, the FDA approved this triple combination for therapeutic use in BRAF V600-mutated melanoma." (PMID 35954441, 2022). "Pyrosequencing revealed a BRAF V600E mutation and the results of histologic and genetic analyses were interpreted as a melanoma." (PMID 35198980, 2022). "Almost all histologic subtypes of melanoma harbor mutations in the BRAF gene, including superficial spreading melanoma, lentigo maligna melanoma, and other types of cutaneous and non-cutaneous melanoma (desmoplastic, acral, Spitz melanoma, etc.)." (PMID 36143375, 2022). "The present study investigated DPG effects in the melanoma cell line (SK-MEL-28) bearing BRAF mutation." (PMID 35806253, 2022). "BRAF are mutant genes expressed in melanoma cells, being associated with tumor cell viability and transformation." (PMID 35456655, 2022). "This, at least in part, ascribes to the fact that melanoma shows high BRAF mutation (50–70% of cases)." (PMID 35372044, 2022). "In melanoma, the use of single gene (BEAMing) assays to detect BRAF V600E mutations in plasma has been challenged by a low sensitivity rate of 75%." (PMID 35347327, 2022). "This is the first study in the literature promoting BRAF/MEK inhibitors as a superior first-line therapy in patient with BRAF-mutated melanoma brain metastases." (PMID 35311078, 2022). "First, we show that SEMA6A protein expression is associated with BRAF mutational status in melanoma patients." (PMID 35440004, 2022). "The results indicated that lj‐2‐66 had higher antitumour activity than chloroquine in melanoma harboring BRAF mutations." (PMID 35332658, 2022). "While the mean age of diagnosis of melanoma in the general population is 63, the mean age of our cohort approaches 69 years old, which corroborates the lower BRAF prevalence and greater percentage of V600K mutations." (PMID 35712493, 2022). "Melanoma is caused by a variety of somatic mutations, and among these mutations, BRAF mutation occurs most frequently and has routinely been evaluated as a critical diagnostic biomarker in clinical practice." (PMID 36181568, 2022). "We found that two PMCA proteins, PMCA1 and PMCA4b, were present in melanoma cells, however, the expression of PMCA4b was downregulated in BRAF mutated cell lines." (PMID 35328746, 2022). "BRAF-mutated melanomas exhibit a high level of aggressiveness and progression, being more predisposed to metastasize, especially to the brain." (PMID 35684471, 2022). "Kinase inhibitors, particularly BRAF and MEK inhibitors, have become the first line of treatment for advanced BRAF-mutated melanoma, which is the most common mutation in cutaneous melanoma." (PMID 35563798, 2022).
melanoma (continued). "Subsequently, the BRAF inhibitors PLX4032 (vemurafenib) and GSK2118436 (dabrafenib) were synthesized and used in the clinical treatment of BRAF mutation melanoma." (PMID 36551302, 2022). "This study demonstrated that the VE1 IHC and BRAF Idylla methods are accurate and highly correlated to the detection of the BRAF V600E mutation in melanoma." (PMID 35328303, 2022). "Mutations in v-Raf murine sarcoma viral oncogene homolog B (BRAF) are prevalent in melanoma, with its subtype BRAFv600E being the most common subtype." (PMID 36612116, 2022). "The BRAF mutation is the most common mutant gene in melanoma and co-occurred with CCND1 amplification in 0.33% (1/302), 1.91% (7/367), and 1.14% (4/350) of tumor samples from the Geneplus, TCGA, and MSKCC cohorts, respectively." (PMID 35844619, 2022). "In a parallel study, we have seen that loss of expression of MST2 and LATS1 is common in melanoma cell lines that have acquired resistance to BRAF inhibitors." (PMID 35941108, 2022). "A mutation in the CDKN2A gene is identified in melanomas of patients whose time to progression was shorter than the median for patients treated with BRAF inhibitors." (PMID 35565444, 2022). "BRAF mutated melanoma cell lines either sensitive or resistant to vemurafenib were susceptible to the induction of cell death by pharmacological ascorbate." (PMID 35406796, 2022). "Although targeted therapies offer a promising avenue for treatment of patients with BRAF-mutated melanoma, most patients experience relapse of disease within a few months." (PMID 36084109, 2022). "The BRAF gene is an oncogene that occurs in 8% of human cancers, while the BRAF mutation usually occurs in melanoma and colorectal cancer." (PMID 35215249, 2022). "Currently, monotherapy with B-Raf inhibitor for the treatment of BRAF-mutated melanoma is subsequently replaced by combination therapy with B-Raf and MEK inhibitors, which target key enzymes in the MAPK signaling pathway (RAS-RAF-MEK-ERK)." (PMID 35408658, 2022). "Of the BRAF mutated primary melanomas, 51.22% (21/41) developed distant metastasis and 75% (9/12) of them finally died of melanoma." (PMID 35326682, 2022). "A biphenotypic epithelioid and plexiform melanoma with DPN-like features was shown to demonstrate BRAF and PTEN mutations in both components but a CTNNB1 mutation only in the DPN-like areas." (PMID 35336833, 2022). "As for NOX5, a recent study combined gene expression and flux balance analysis of BRAF-mutant melanomas to reveal the upregulation of NOX5 expression that is associated with the resistance to BRAF inhibitor treatment." (PMID 35326683, 2022). "In a separate study, 84 patients with BRAF V600-mutated unresectable melanoma were started on dabrafenib alone and then switched to a dabrefenib and trametinib combination before disease progression." (PMID 35954441, 2022). "In patients with melanoma with BRAF V600 mutation, ICIs and tyrosine kinase inhibitor therapy are both potential options." (PMID 35703181, 2022). "Aiming to mimic the clinical disease setting, we first injected orthotopically the murine D4M.3A melanoma cells, which bear the BRAF V600E mutation, into C57BL/6J mice." (PMID 36168618, 2022). "BRAF and MEK inhibitors have revolutionized melanoma therapy throughout recent years and are prescribed for patients with melanoma that harbor a BRAF mutation, present in about 60% of melanoma." (PMID 35558554, 2022). "Melanoma cells are frequently characterized by oncogenic BRAF mutations that cause the constitutive activation of the MAPK/ERK mitogenic pathway, resulting in increased cell proliferation." (PMID 36009541, 2022). "Herein, we report two patients with a mucosal melanoma in which a BRAF mutation was identified, and in whom, only after thorough examination of the skin, eventually a primary cutaneous melanoma was found." (PMID 34142226, 2022).
melanoma (continued). "The described pattern of NF1 mutant melanoma having the largest number of mutations within the three main subtypes of BRAF, NRAS, or NF1-mutated melanomas was apparent in our ARID1A mutated cohort." (PMID 35565222, 2022). "Oncogenic mutations in the v-Raf murine sarcoma viral oncogene homolog B (BRAF) gene are present in about 50% of melanomas and cause fast disease progression with especially poor prognosis." (PMID 35406796, 2022). "The inhibition of BRAF (a TME component) stimulates melanoma-associated fibroblasts, resulting in focal adhesion kinase (FAK)-dependent melanoma survival signaling." (PMID 35814435, 2022). "The most frequent mutations in melanoma affect the BRAF oncogene, a protein kinase of the MAPK signaling pathway." (PMID 35494017, 2022). "Montagnani and colleagues predicted ADCK2 as a metastasis-associated gene in melanoma, especially in BRAF-mutated melanoma." (PMID 35205819, 2022). "Xenograft melanomas from BRAF-mutated patients were treated with RAF/MEK inhibition followed by the induction of an MRD model." (PMID 35784923, 2022). "BRAF mutations are common in melanoma (50%), thyroid papillary cancers (approximately 35%), and colorectal cancers (5%–10%)." (PMID 36189283, 2022). "Vemurafenib is a targeted therapy approved for the management of patients with metastatic or unresectable melanoma with BRAF V600E mutation at the dosage of four tablets of 240 mg every 12 h." (PMID 35742834, 2022). "Of note, the BRAF V600 mutation status is usually consistent between primary melanomas and matched metastases, even after targeted therapy." (PMID 35328303, 2022). "BRAF mutation is a prominent feature of melanoma, which activates the downstream kinase MEK/ERK within the MAPK pathway, promoting melanoma progression." (PMID 36700470, 2022). "It appears that this melanoma underwent metaplastic change to resemble desmoplastic melanoma and acquired the associated biological characteristics, but it retained the BRAF mutation and eventually has reverted to biological behavior more typical of SSM." (PMID 34286349, 2022). "The same observations have been made in BRAF-mutated melanoma, glioblastoma, and colorectal cancers upon BRAF inhibitors." (PMID 35681591, 2022). "These therapies targeted mutated BRAF, present in 40–60% of patients with melanoma, and improved the overall survival to 50% at 17 months, however, these results are typically followed by relapse." (PMID 36076924, 2022). "BRAF mutations are found in about 50% of all individuals with melanoma and 10% of those with colorectal cancer (CRC)." (PMID 36589179, 2022). "OncoKB lists BRAF V600E as a level 1 actionable variant, which was present in 9 cell lines (7 melanoma and 2 colorectal cell lines) in the NCI-60 dataset." (PMID 35525914, 2022). "This molecular subtype stratification of patients is very relevant because about 50% of melanoma patients have a mutation in the BRAF gene." (PMID 35040264, 2022). "In the case of BRAF V600 mutated melanoma, it can be offered instead of BRAF/MEK inhibitor combined therapy or after tumor progression on the latter therapy." (PMID 36844955, 2022). "It is noteworthy that more than half of the melanomas evidence BRAF V600 mutations with ∼25% of neuroblastoma RAS viral oncogene homolog (NRAS) gene mutations." (PMID 35360535, 2022). "Subsequently, inhibitors of BRAF mutation are of great attention as effective sighted prevention mechanisms (i.e., therapies) for melanomas sheltering BRAF mutations." (PMID 36551688, 2022). "Adjuvant therapy with PGA-SLM-mDBF combined with ICPi, was well-tolerated and resulted in prolonged survival and prevention of peritoneal and brain metastases formation in BRAF-mutated melanoma-bearing mice." (PMID 36168618, 2022). "BRAF with a V600E mutation is a well-established oncogene in melanoma and colorectal cancer, but it is rarely found in breast cancer." (PMID 36011019, 2022).
melanoma (continued). "In patients with advanced melanoma, approximately one-half harbor a mutation in the BRAF gene, and they experience significant long-term treatment benefit from targeted therapy with BRAF or MEK (mitogen-activated protein kinase) inhibitors." (PMID 36361209, 2022). "The recently published IMspire150 phase III trial by Genentech, Inc., Exelixis, and Roche investigated the effect of a three-part combination of atezolizumab, vemurafenib, and cobimetinib in advanced BRAF-mutated melanoma." (PMID 35954441, 2022). "An interesting potential role for CDK inhibitors in melanoma is to use these molecules in association with BRAF and MEK inhibitors." (PMID 35053435, 2022). "Our results have unraveled a novel and potentially interesting association between PD-L1+ PMNs and BRAF status in melanoma patients." (PMID 36016960, 2022). "Mutations in BRAF occur in approximately 50% of malignant melanomas, and 90% of them involve codon 600 and the substitution of valine with glutamic acid (V600E), and 5–6% the substitution of valine with lysine (V600 K)." (PMID 35406444, 2022). "In melanoma, the BRAF V600E mutation has been proposed as a source of deregulated mitotic checkpoint signaling." (PMID 36276131, 2022). "Zhang found that many of these tumors are associated with BAP1 mutations, compared with nodular melanoma or superficial spreading melanoma, which are associated with BRAF and NRAS mutations." (PMID 36289768, 2022). "While BRAF inhibitors have been approved to treat melanoma in patients with activating BRAF mutations, several patients have innate or acquired resistance to BRAF inhibitors." (PMID 35525274, 2022). "In patients with melanoma, the activated BRAF-mutated kinase can be inhibited by BRAF-targeting drugs, and its downstream protein mitogen-activated protein kinase kinase (MEK) can be inhibited by a MEK-targeting drug." (PMID 35379799, 2022). "This highlights the need for any melanoma detection assay to include TERT promoter mutations in order to maximize detection rates in BRAF/NRAS WT patients." (PMID 35494035, 2022). "In total, 16 studies have already reported a comparison between the Idylla method and other molecular reference methods for the assessment of the BRAF V600E mutation in melanoma patients at the time of the publication." (PMID 35328303, 2022). "In cutaneous (CSD/NCSD) melanoma, the most frequently mutated gene was BRAF (56.1%, 23/41), which was similar to that in western population." (PMID 35688842, 2022). "Higher expression of SCD1 increased the activity of YAP/TAZ, a stem cell pathway, which supported the stemness and adapted to BRAF inhibitor (vemurafenib) and MEK inhibitor (binimetinib) treatments in BRAF-mutated melanoma." (PMID 35646898, 2022). "Melanoma cells harboring mutations in the B-Raf proto-oncogene serine/threonine kinase (BRAF) gene, which is considered a genetic hallmark of >50% of melanoma, showed higher levels of Cav 3.1 and Cav 3.3 mRNA." (PMID 36077291, 2022). "Collectively, our results suggest that HSPB8 has an antitumoral action in melanoma cells characterized by BRAF and NRAS mutations." (PMID 36400750, 2022). "In order to prevent early resistance to BRAF inhibition, the BRAF inhibitor dabrafenib can be combined with the MEK inhibitor trametinib according to protocols established for BRAF mutated melanoma." (PMID 35864412, 2022). "Mutations in the NF1 gene leading to the inactivation of the encoded protein occur in melanoma with a frequency of 12–30% and are the third most frequent mutation in melanoma (after BRAF and NRAS)." (PMID 35565444, 2022). "For BRAF-wildtype melanomas and for BRAF-mutated melanoma, especially those that have become resistant to BRAF inhibitors, targeting the downstream consequences of MAPK pathway activation is of interest." (PMID 35409102, 2022).
melanoma (continued). "These outcomes underline the crucial function of BRAF in melanoma in terms of genesis and progression." (PMID 36551688, 2022). "Both soluble and EV-associated NKG2D-ligands, generally decreased in BRAF-mutant melanoma cell supernatants after MAPKi in vitro, replicating cell surface expression." (PMID 36726591, 2022). "In this way, activation of the Rho signalling can cause BRAF-inhibitor resistance and was described as a hallmark of therapy resistance in melanoma." (PMID 35883549, 2022). "As BRAF mutation is also common in melanoma, BRAF inhibitors can shrink or slow the growth of metastatic melanoma in patients harbouring this mutation." (PMID 35328664, 2022). "Our findings provide a rationale for designing clinical trials with nintedanib and potentially other anti‐fibrotic agents to enhance treatment efficacy in BRAF‐mutated melanoma patients." (PMID 35156321, 2022). "BRAF-mutated melanoma cells were more sensitive to fisetin exposure, and this was linked with the phosphorylation of MEK1/2 as well as to ERK1/2 reduction." (PMID 36558146, 2022). "Tumors with the BRAF mutations often demonstrate a more aggressive clinical course, as it was seen in melanoma and thyroid cancer." (PMID 37065428, 2022). "Although BRFA inhibitors are quite effective in BRAF-mutated melanoma patients, most of the patients develop a secondary resistance after an effective treatment." (PMID 35401191, 2022). "The prevalence and function of TNFR2 on melanomas, especially in the context of BRAF-mutated melanomas, is poorly understood." (PMID 35879777, 2022). "The authors showed that the knockout of ATOX decreased ERK1/2 phosphorylation and reduced cell growth in A375 and WM888 melanoma cell lines harboring the oncogenic mutations in the Ser/Thr kinase BRAF." (PMID 36291728, 2022). "The present work has evaluated the overall clinical performance of IdyllaTM Biocartis in the characterization of BRAF/NRAS-mutated melanoma patients, either in radically operated stage III–IV or in locally advanced/metastatic ones." (PMID 35804825, 2022). "Then, sample data from 487 PTC patients (198 with BRAFwt and 289 with BRAFmut) and 469 melanoma patients (229 with BRAFwt and 240 with BRAFmut) extracted from the TCGA were divided into two groups according to the BRAF mutation status." (PMID 35136031, 2022). "In 2020, the results of the IMspire150 trial showed that adding atezolizumab to BRAFi/MEKi in patients with BRAF(V600)-mutated advanced melanoma resulted in improved PFS with acceptable tolerance." (PMID 36698407, 2022). "In BRAF V600–mutated melanoma patients, treatment with the combination of atezolizumab (anti-PD-L1) plus vemurafenib (BRAF inhibitor) + cobimetinib (MEK inhibitor) promoted 71.8% objective responses (a complete response rate of 20%)." (PMID 36189283, 2022). "The expert panel of oncologists and pathologists from Argentina, Brazil, Colombia, Costa Rica, and Mexico shared their experiences and polled colleagues to provide insight into current clinical practice for patients with BRAF-mutated melanoma and CRC." (PMID 36589179, 2022). "The high frequency of BRAF V600K mutations observed in SM can partially explain the unique behavior of this subgroup of melanomas." (PMID 36064728, 2022). "In complement to CDK12 kinase activity, we measured RPB1 phosphorylation and the expression of CDK12 target genes in BRAF-mutated melanoma cell lines." (PMID 36309522, 2022). "KRAS or HRAS mutations are detected infrequently in approximately 5% of melanoma patients, whereas NRAS mutations (NRASmut) are found in about 25% of patients, which makes NRAS the second most frequent mutation type after BRAF in melanoma." (PMID 36551302, 2022). "Differing from the experience in melanoma, BRAF V600E mutations only accounted for 20–30% of the BRAF alterations seen in PDAC and pancreatic acinar cell carcinomas." (PMID 36551707, 2022).